CAND1 (cullin associated and neddylation dissociated 1)
Description:
Key assembly factor of SCF (SKP1-CUL1-F-box protein) E3 ubiquitin ligase complexes that promotes the exchange of the substrate-recognition F-box subunit in SCF complexes, thereby playing a key role in the cellular repertoire of SCF complexes. Acts as a F-box protein exchange factor. The exchange activity of CAND1 is coupled with cycles of neddylation conjugation: in the deneddylated state, cullin-binding CAND1 binds CUL1-RBX1, increasing dissociation of the SCF complex and promoting exchange of the F-box protein. Probably plays a similar role in other cullin-RING E3 ubiquitin ligase complexes.
Synonyms: KIAA0829; TIP120; TIP120A; DKFZp434M1414
Tractability: Antibody: its Gene Ontology location is reachable by antibodies, with high confidence. PROTAC: ubiquitination databases record sites on it; its protein half-life has been measured.
Gene: Protein-coding gene on chromosome 12 (67,269,358 to 67,319,953, forward strand). Ensembl gene ENSG00000111530.
Subcellular location: Cytoplasm; Nucleus
Subcellular location (Human Protein Atlas): Cytosol; Golgi apparatus; Nucleoplasm
Pathways (Reactome):
Immune System: Neutrophil degranulation
Metabolism of proteins: Neddylation
Transport of small molecules: Iron uptake and transport
Gene Ontology:
Molecular function: protein binding; TBP-class protein binding
Biological process: cell differentiation; negative regulation of catalytic activity; protein ubiquitination; SCF complex assembly; positive regulation of DNA-templated transcription; positive regulation of RNA polymerase II transcription preinitiation complex assembly
Cellular component: cullin-RING ubiquitin ligase complex; cytoplasm; cytosol; extracellular exosome; membrane; nucleoplasm; nucleus; ubiquitin ligase complex; extracellular region; ficolin-1-rich granule lumen; secretory granule lumen
Genetic constraint (gnomAD): Loss-of-function variants: 2 observed, 83.33 expected, observed/expected ratio (o/e) 0.024, 90% interval 0.009 to 0.076. The upper end of that interval is the gene's LOEUF score, 0.076, which puts it in group 1 of 6, group 1 being the genes least tolerant of losing a copy. Missense variants: 780 observed, 1,246.2 expected, observed/expected ratio (o/e) 0.63, 90% interval 0.59 to 0.66. Synonymous variants: 436 observed, 444.05 expected, observed/expected ratio (o/e) 0.98, 90% interval 0.91 to 1.06.
Homologues: Orthologues: macaque CAND1 (100% identical), chimpanzee CAND1 (99% identical), dog CAND1 (99% identical), guinea pig CAND1 (99% identical), pig CAND1 (99% identical), rat Cand1 (99% identical), mouse Cand1 (99% identical), rabbit CAND1 (98% identical), tropical clawed frog cand1 (98% identical), zebrafish cand1 (94% identical), Caenorhabditis elegans cand-1 (38% identical). Paralogues in human: CAND2 (63% identical).
Diseases named in the same sentence as CAND1 in open-access papers:
CAND1 is named in the same sentence as 33 diseases in open-access papers, as found by Europe PMC text mining. Sharing a sentence is not in itself a finding about the gene and the disease. The quoted sentences say what the papers report.
prostate carcinoma (11 papers, 2013 to 2026). A carcinoma that arises from epithelial cells of the prostate gland. "CAND1 overexpression was linked to decreased overall survival in breast and prostate cancer." (PMID 41299419, 2025). "Another argument speaking in favor of the model presented in our work is that low Cand1 expression in primary prostate carcinoma tissue could be linked to better patient survival in four out of five investigated study cohorts." (PMID 32059441, 2020). "Bioinformatic analyses of human prostate cancer clinical datasets revealed that CAND1 mRNA level correlated with disease status, with higher expression correlated with metastatic prostate cancer and poorer patient survival." (PMID 42133602, 2026). "Knockdown of CAND1 in prostate cancer cells reduced the expression of AR and ARv7 target genes, supporting its role as a coactivator." (PMID 42133602, 2026). "The knockdown of CAND1 results in decreased cell viability, proliferation, and induced apoptosis in drug-resistant prostate cancer cell lines." (PMID 41299419, 2025). "CAND1 has been implicated in mediating carcinogenesis, in which the downregulation of CAND1 induces apoptosis in prostate cancer cell lines." (PMID 36292029, 2022). "Other published reports show that CAND1 is overexpressed in prostate cancer tissue compared to normal tissue." (PMID 36292029, 2022). "An analysis of 13 prostate cancers showed that overexpression of CAND1 resulted in malignant progression." (PMID 28654678, 2017). "Additionally, CAND1 has been shown to serve as a potential biomarker for worse prognosis in liver and prostate cancers." (PMID 36292029, 2022). "In addition, CAND1 overexpression has been shown to promote the proliferation of prostate cancer by stabilizing PLK4." (PMID 36292029, 2022). "We could show that Cand1 is expressed in the nucleus as well as in the cytoplasm of benign and prostate carcinoma cells." (PMID 32059441, 2020). "Several evidence have indicated the disruption of CAND1 in prostate cancer." (PMID 29568567, 2018). "Notably, a previous study reported that CAND1 promoted PLK4-regulated centriole over-duplication in prostate cancer, indicating the potential role of PLK4 in prostate cancer." (PMID 35387563, 2022). "However, the role of Cand1 in prostate cancer (PCa) has not been intensively investigated so far." (PMID 32059441, 2020). "Although the role of CAND1 in mediating invasion in breast cancer has not been investigated yet, CAND1 has been shown to stabilize and synergize with PLK4 to induce centriole overduplication in prostate cancer." (PMID 36292029, 2022).
liver cancer (6 papers, 2020 to 2024). An epithelial or non-epithelial malignant neoplasm that arises from the liver. "CAND1 downregulation significantly reduced the tumour burden in a primary mouse liver cancer model and a PDX model." (PMID 37837399, 2023). "We further tested the in vivo function of CAND1 in xenograft mouse liver cancer models." (PMID 37837399, 2023). "Moreover, it has been shown that CAND1 correlates with poor OS in liver cancer, in which silencing CAND1 suppresses the proliferation of liver cancer by inducing caspase-8/RIP1-dependent apoptosis." (PMID 36292029, 2022). "In addition, CAND1 upregulation compared to normal tissue has also been observed in other cancers, including prostate and liver cancers." (PMID 36292029, 2022). "Therefore, targeting the CAND1-SCFFBXO11-HNRNP A2/B1 axis may be a potential therapeutic strategy for liver cancer." (PMID 39366930, 2024). "In addition, CAND1 is an established prognostic biomarker for worse prognosis in liver cancer." (PMID 36292029, 2022). "In liver cancer PDX mouse models and primary HCC mouse models, CAND1 knockdown significantly inhibited lipid accumulation and tumour growth in vivo." (PMID 37837399, 2023). "Additionally, knockout of CAND1, a regulator of Cullin–RING ubiquitin ligases, suppressed liver cancer cell proliferation by activating apoptosis." (PMID 37999208, 2023).
hepatocellular carcinoma (3 papers, 2021 to 2025). A malignant tumor that arises from hepatocytes. "Correlation between cullin‐associated and neddylation‐dissociated 1 (CAND1) expression and clinicopathologic characteristics of hepatocellular carcinoma patients." (PMID 37837399, 2023). "Targeting CAND1‐SCF(FBXO11)‐hnRNPA2B1 axis may be a novel strategy against hepatocellular carcinoma." (PMID 37837399, 2023). "CAND1 regulates the reprogramming of lipid metabolism through SKP1-Cullin-1-F-box (SCF,E3 ligase)-mediated heterogeneous nuclear ribonucleoprotein A2/B1 ubiquitination, promoting hepatocellular carcinoma." (PMID 39944823, 2025).
breast carcinoma (2 papers, 2021 to 2022). "Prompted by the lack of information about CAND1’s potential as an ERα-positive breast cancer biomarker, comprehensive bioinformatics analysis was carried out utilizing several databases to evaluate the significance of CAND1 as a diagnostic tool." (PMID 36292029, 2022). "In addition, CAND1 might mediate metastasis through the interaction with miR-148b-3p, which has been implicated in mediating the migration of breast cancer cell lines; however, the exact mechanism remains to be unidentified." (PMID 36292029, 2022). "The prognostic value of CAND1 in ERα-positive breast cancer was explored using the Kaplan–Meier plotter website." (PMID 36292029, 2022). "In conclusion, it was shown that CAND1 is significantly upregulated in breast cancer patients compared to normal breast tissue, and higher CAND1 expression was observed in histologic grade 3 compared to grades 2 and 1 in ERα-positive breast cancer patients." (PMID 36292029, 2022). "Such analysis will aid in the development of novel therapeutics specifically targeted at Erα-positive breast cancer patients with upregulated CAND1." (PMID 36292029, 2022). "The genes that showed a significant positive Pearson’s correlation (correlation coefficient > 0.5) with CAND1 in ERα-positive breast cancer patients were selected." (PMID 36292029, 2022). "CAND1 mRNA significantly correlates with lymph nodes examined positive in ERα-positive breast cancer patients." (PMID 36292029, 2022). "It was observed that the genes that significantly correlate with CAND1 expression in ERα-positive breast cancer patients were involved in the activation of the androgen and estrogen signaling pathways." (PMID 36292029, 2022). "TUBB, which interacts with CAND1, has also been shown to correlate with poor OS in ERα-positive breast cancer." (PMID 36292029, 2022). "Significant upregulation of CAND1 mRNA expression was observed in breast cancer tissue compared to normal breast tissue." (PMID 36292029, 2022). "The Gene Set Cancer Analysis (GSCA) web server was then used to explore the pathways of the genes that correlate with CAND1 in ERα-positive breast cancer." (PMID 36292029, 2022). "A published report showed similar results, in which higher CAND1 was observed in breast cancer with lymph node metastasis compared to breast cancer without lymph node metastasis." (PMID 36292029, 2022). "CAND1 mRNA expression in ERα-positive breast cancer patients was explored using Bc-GenExMiner and TIMER2.0." (PMID 36292029, 2022). "In this study, Breast Cancer Gene-Expression Miner (Bc-GenExMiner) and TIMER2.0 were utilized to explore the mRNA expression of CAND1 in ERα-positive breast cancer patients." (PMID 36292029, 2022). "The METABRIC dataset in the cBio Cancer Genomics Portal was explored to validate our observation that CAND1 correlates with worse prognosis in ERα-positive breast cancer patients." (PMID 36292029, 2022). "It was vital to investigate the genes that show a significant positive correlation with CAND1 in ERα-positive breast cancer patients to explore the pathways in which CAND1 exerts its effect on prognosis, as described in the summary of the experimental design." (PMID 36292029, 2022). "In conclusion, the results suggest that CAND1 could be used as a potential novel biomarker for worse prognosis in ERα-positive breast cancer." (PMID 36292029, 2022). "In addition, significantly higher CAND1 mRNA was observed in ERα-positive breast cancer patients who received hormone therapy compared to ERα-positive breast cancer patients who did not receive hormone therapy." (PMID 36292029, 2022). "This suggests that the correlation observed between CAND1 and metastasis in ERα-positive breast cancer might be due to the activation of the estrogen and androgen signaling pathways." (PMID 36292029, 2022).
breast carcinoma (continued). "Therefore, we evaluated the significance of CAND1 expression in ERα-positive breast cancer via bioinformatics analysis of the clinical indicators and survival data in several large online databases, including Bc-GenExMiner and TIMER2.0." (PMID 36292029, 2022). "Our results suggest that CAND1 might mediate invasion and metastasis in ERα-positive breast cancer, possibly through the activation of the estrogen and androgen signaling pathways." (PMID 36292029, 2022). "Our results showed that CAND1 might be involved in the activation of the androgen and estrogen signaling pathways in ERα-positive breast cancer, as the genes that strongly correlate with CAND1 in ERα-positive breast cancer were involved in activating these pathways." (PMID 36292029, 2022). "It was observed that CAND1 significantly correlates with worse OS, worse DMFS, and worse RFS in ERα-positive breast cancer patients." (PMID 36292029, 2022). "Interestingly, CAND1 interacts with CUL4, which is a cullin family member that has been shown to correlate with poor OS in breast cancer." (PMID 36292029, 2022). "The significant negative correlations between CAND1 and several immune cells agree with our previous observation that CAND1 correlates with poor prognosis in ERα-positive breast cancer." (PMID 36292029, 2022). "A published report agrees with our findings, showing that CAND1 was upregulated in ERα-positive breast cancer compared to ERα-negative breast cancer." (PMID 36292029, 2022). "Significant upregulation of CAND1 mRNA expression was also observed in ERα-positive breast cancer patients compared to ERα-negative breast cancer, tumor adjacent, and normal breast tissue." (PMID 36292029, 2022). "In addition, it was found that CAND1 correlates positively with DMSF and lymph nodes in ERα-positive breast cancer patients." (PMID 36292029, 2022). "Although the prognostic value of CAND1 in ERα-positive breast cancer has not been extensively studied, it has been suggested that CAND1 correlates with worse OS in breast cancer." (PMID 36292029, 2022). "Given that CAND1 correlates positively with DMSF and lymph nodes in ERα-positive breast cancer patients, CAND1 might be involved in mediating invasion and metastasis in ERα-positive breast cancer patients." (PMID 36292029, 2022). "Although the role of CAND1 in regulating the estrogen signaling pathway has not been extensively studied, it has been observed that the estrogen receptor positively regulates CAND1 in ERα-positive breast cancer cell lines." (PMID 36292029, 2022). "However, the prognostic significance of CAND1 in breast cancer has not yet been explored." (PMID 36292029, 2022). "Although the correlation between CAND1 and the infiltration of immune cells in breast cancer has not been studied before, a published report showed that the infiltration of CD4 memory T cells and neutrophils correlates positively with CAND1 in lung adenocarcinoma." (PMID 36292029, 2022).
pulmonary fibrosis (2 papers, 2024 to 2025). Chronic progressive interstitial lung disorder characterized by the replacement of the lung tissue by connective tissue, leading to progressive dyspnea, respiratory failure, or right heart failure. "Celastrol is a pentacyclic triterpene compound isolated from Tripterygium wilfordii as a novel treatment for pulmonary fibrosis; it exhibits antifibrotic effects through the covalent linkage of CAND1 at the Cys264 residue." (PMID 39697538, 2024). "The knockdown of CAND1 in pathological cells could decrease the inhibitory effect of CEL on fibroblast‐myofibroblast transformation (FMT), providing evidence that the anti‐pulmonary fibrosis activity of CEL was dependent on CAND1 [17c]." (PMID 40873643, 2025).
Alzheimer disease (1 paper, 2014). A progressive, neurodegenerative disease characterized by loss of function and death of nerve cells in several areas of the brain leading to loss of cognitive function such as memory and language. "Two interactors have been associated with Alzheimer's disease (CAND1, UBE2I), but none have yet been associated with neuropsychiatric disorders." (PMID 25414627, 2014).
esophageal cancer (1 paper, 2022). A primary or metastatic malignant neoplasm involving the esophagus. "Collectively, findings obtained in the current in silico study provide evidence for the prognostic evaluation in esophageal cancer following radiotherapy by targeting the miR-132-3p/CAND1/ZDHHC23 and miR-576-5p/AHR pathways." (PMID 36456979, 2022). "Our study demonstrated that miR-132-3p/CAND1/ZDHHC23 and miR-576-5p/AHR were critical molecular pathways related to the radiosensitivity of esophageal cancer." (PMID 36456979, 2022). "Altogether, the miR-132-3p/CAND1/ZDHHC23 and miR-576-5p/AHR pathways could affect radiosensitivity in esophageal cancer." (PMID 36456979, 2022). "The prognostic risk model based on 2 miRNAs (miR-132-3p and miR-576-5p) and 4 mRNAs (CAND1, ZDHHC23, AHR, and MTMR4) could accurately predict the prognosis of esophageal cancer patients." (PMID 36456979, 2022). "Furthermore, we uncovered that the prognostic risk model based on 2 miRNAs (miR-132-3p and miR-576-5p) and 4 mRNAs (CAND1, ZDHHC23, AHR, and MTMR4) could accurately and effectively predict the prognosis of patients with esophageal cancer." (PMID 36456979, 2022). "Additionally, our findings indicated that the miR-132-3p/CAND1/ZDHHC23 and miR-576-5p/AHR pathways could influence radiosensitivity in esophageal cancer." (PMID 36456979, 2022). "Ultimately, 2 miRNAs (namely, miR-132-3p and miR-576-5p) and 4 mRNAs (namely, CAND1, ZDHHC23, AHR, and MTMR4) were obtained followed bioinformatics analyses, and possessed the potential to serve as prognostic biomarkers for radiosensitivity in esophageal cancer patients." (PMID 36456979, 2022). "Finally, it was verified that miR-132-3p/CAND1/ZDHHC23 and miR-576-5p/AHR could affect the radiosensitivity in esophageal cancer." (PMID 36456979, 2022).
Glucose intolerance (1 paper, 2023). Glucose intolerance (GI) can be defined as dysglycemia that comprises both prediabetes and diabetes. "Furthermore, CAND1 KO+/--HFD mice developed more serve glucose intolerance and insulin resistance upon HFD challenge than WT-HFD mice, as revealed by the glucose tolerance test (GTT) and insulin tolerance test (ITT)." (PMID 37528093, 2023).
Hepatic steatosis (1 paper, 2023). Steatosis is a term used to denote lipid accumulation within hepatocytes. "In contrast to the alterations observed in CAND1 cKO mice, hepatocyte-specific overexpression of CAND1 substantially protected against HFD-induced hepatic steatosis, hepatic resistance and inflammation." (PMID 37528093, 2023). "A large number of E3 ubiquitin ligases and their regulatory genes were altered during liver steatosis, including CRLs regulator CAND1." (PMID 37528093, 2023). "Specifically, overexpression of CAND1 in hepatocytes ameliorated hepatic steatosis, and decreased LW/BW ratio and liver contents of TG and TC." (PMID 37528093, 2023). "We discovered that CAND1 was markedly downregulated during hepatic steatosis." (PMID 37528093, 2023). "However, whether CAND1 plays a role in NAFLD, particularly in the vicious cycle of hepatic steatosis, insulin resistance, and inflammation, remains to be explored." (PMID 37528093, 2023).
Insulin resistance (1 paper, 2023). Increased resistance towards insulin, that is, diminished effectiveness of insulin in reducing blood glucose levels. "We observed that CAND1 KO+/--HFD mice exhibited higher fasting glucose levels, fasting insulin levels, and homeostatic model assessment of insulin resistance (HOMA-IR) compared with WT-HFD mice." (PMID 37528093, 2023).
lung carcinoma (1 paper, 2022). "Cullin-associated and neddylation-dissociated 1 (CAND1) has been implicated in mediating carcinogenesis in prostate and lung cancers." (PMID 36292029, 2022). "CAND1 has also been implicated in mediating proliferation and metastasis in lung cancer, in which targeting CAND1 by miR-33a decreases the proliferation and migration." (PMID 36292029, 2022).